TRPC1 (transient receptor potential cation channel subfamily C member 1)
Diseases named in the same sentence as TRPC1 in open-access papers (continued):
Sharing a sentence is not in itself a finding about the gene and the disease.
asthma (8 papers, 2017 to 2025). "In guinea pigs with asthma, expression of the TRPC1 channel has also been linked to the development of chronic airway inflammation." (PMID 40533673, 2025). "TRPC1 has also been implicated in the inflammation associated with asthma." (PMID 38365763, 2024). "TRPC1 plays an important role in airway remodeling and has a significant clinical therapeutic effect on asthma." (PMID 38033335, 2023). "It proved that TRPC1 plays an important role in airway remodeling, which represents significant clinic therapeutic effect in asthma." (PMID 31092255, 2019). "Therefore, in obese asthma patients, the activity of the TRPC1 channel will determine the development of the disease." (PMID 38365763, 2024). "Mechanistically, BCYRN1 increased TRPC1 via developing the stability of TRPC1, thus promoting ASMCs proliferation, which provided a novel sight to attenuate abnormal proliferation and migration of ASMCs in asthma." (PMID 33013382, 2020). "The development of drugs that target the function and expression of TRPC1 may be an additional strategy for developing novel therapeutic approaches for asthma that prevent progressive airway remodeling." (PMID 31092255, 2019). "However, the relationships among IL-4, TRPC1 and mucus overproduction in bronchial epithelial cells (BECs) in asthma are poorly understood." (PMID 28931396, 2017). "TRPC1 may act indirectly as an agonist, leading to obese asthma." (PMID 38365763, 2024). "Given the complexity and uniqueness of obese asthma, we have identified three TRP channels – TRPV1, TRPM8, and TRPC1 – and examined their role in immune cells, particularly macrophages." (PMID 38365763, 2024). "However, the role of lipid rafts/TRPC1 and Ca2+ influx in BECs of asthma is unknown." (PMID 28931396, 2017). "Due to the high expression of certain TRP channels, particularly in immune cells like macrophages, and the findings from previous research, as well as their clear or potential involvement in the inflammatory process of obese asthma, we have specifically chosen to discuss TRPV4, TRPM8, and TRPC1." (PMID 38365763, 2024).
gastric cancer (8 papers, 2011 to 2024). A primary or metastatic malignant neoplasm involving the stomach. "TRPC1 exacerbated EMT in gastric cancer via ciRS-7/miR-135a-5p/TRPC1 axis." (PMID 39678511, 2024). "In gastric cancer cells, a role for the TRPC1/3/6 in TGFβ-induced EMT was described." (PMID 34360952, 2021). "Although either TRPC1 channel or Ca2+ entry mode of NCX1 is implicated in some tumorigenesis, it has not been explored if a coordination of NCX1 and TRPC1 involves in the pathogenesis of H. pylori-associated human gastric cancer (GC)." (PMID 35882979, 2022). "Together with TRPC1 and TRPC3, a role for TRPC6 in TGFβ-induced EMT was described in gastric cancer cells, mediated via the Ras/Raf1/ERK1/2 signaling cascade." (PMID 34360952, 2021). "Moreover, Zhang and colleagues supported the results for TRPC1, where they found TRPC1 mediated EMT (epithelial-mesenchymal transition) exacerbation in gastric cancer." (PMID 35685622, 2022). "Blockade of TRPC1 and TRPC6 also holds considerable potential in GI oncology, given that TRPC1 may promote pancreatic cancer cell invasion and TRPC6 seems to play a significant role in human esophageal and gastric cancer development." (PMID 21420431, 2011).
metabolic syndrome (8 papers, 2017 to 2025). A cluster of metabolic risk factors for CARDIOVASCULAR DISEASES and TYPE 2 DIABETES MELLITUS. "Building upon the dyslipidemia phenotype observed in endothelial TRPC1 deficiency, we conducted untargeted serum metabolomic profiling across four experimental groups: CTL-TRPC1EC−/−, CTL-TRPC1fl/fl, DIO-TRPC1EC−/−, and DIO-TRPC1fl/fl." (PMID 40568618, 2025). "One study suggested that TRPC1 was elevated in a porcine model of metabolic syndrome produced by feeding 6–9-month-old pigs a HFD." (PMID 41009007, 2025). "One study suggested that TRPC1 is elevated in a porcine model of metabolic syndrome produced by feeding 6- to 9-month-old pigs a high-fat diet, but no causal relationship was suggested or defined." (PMID 38885005, 2024). "This strengthens our hypothesis that metabolic syndrome can be created by the deletion of both copies of the Trpc1 gene." (PMID 38885005, 2024). "The data provided above show an important role for TRPC1 in the onset of metabolic syndrome." (PMID 29074621, 2017). "Since elevated aldosterone is a feature of metabolic syndrome, we hypothesized that higher TRPC1 immunostaining in MetS atheromas may be due to an aldosterone-dependent increase in monocyte adhesion to the coronary endothelium and that spironolactone may decrease monocyte adhesion." (PMID 28756533, 2017). "Notably, endothelial TRPC1 deficiency exacerbated these lipid abnormalities under obese conditions: DIO-TRPC1EC−/− mice displayed significantly increased levels of TC, LDL-C, and TG, along with further reductions in HDL-C compared to DIO-TRPC1fl/fl mice, indicating exacerbated dyslipidemia." (PMID 40568618, 2025). "Nonetheless, aldosterone promotes an MR-specific increase in TRPC1/5 and STIM1 protein expression in ARVMs, as seen in metabolic syndrome adrenal chromaffin cells, in coronary arteries, and in NRVMs." (PMID 31878108, 2019). "The promoter regions of TRPC1 and TRPC6 possess half-site glucocorticoid/mineralocorticoid response elements driving the expression of these TRPC channels in metabolic syndrome, characterized by elevated plasma aldosterone." (PMID 28756533, 2017). "Previously, we reported that TRPC1 and TRPC6 expression is markedly elevated in metabolic syndrome pig coronary arteries." (PMID 28756533, 2017).
pulmonary hypertension (8 papers, 2012 to 2025). Increased pressure within the pulmonary circulation due to lung or heart disorder. "Most importantly, it was shown that the expression of TRPC1 and TRPC6 is upregulated in PASMC of hypoxia-induced pulmonary hypertension, a cause for an increase in SOCE and ROCE." (PMID 23056939, 2012). "Additionally, sildenafil and sodium tanshinone IIA sulfonate suppresses TRPC1 and TRPC6 expressions in the treatment of experimental pulmonary hypertension." (PMID 34174803, 2021). "To date, no pharmacological modulators of TRPC1/4/5 have been reported in models of pathological cardiac remodelling or pulmonary hypertension." (PMID 29865154, 2018). "However, TRPC1/4/5 channels have been implicated in various human diseases, including seizures (TRPC5 and TRPC1:C4), fear-related behaviour (TRPC5), severe pulmonary arterial hypertension (TRPC4), heart failure (TRPC1/C4), and chemotherapeutic resistance of cancers (TRPC5)." (PMID 29865154, 2018).
endometrial cancer (7 papers, 2020 to 2025). Primary or metastatic malignant neoplasm involving the endometrium (mucous membrane that lines the endometrial cavity). "In contrast, the over-expression of TRP family members TRPV2 and TRPC1 in the same study of endometrial cancer cells was associated with the Epithelial–Mesenchymal Transition and more aggressive tumors." (PMID 40332161, 2025). "As such, TRPV2 and TRPC1 are associated with the mesenchymal cell phenotype and are upregulated in both endometrial cancer biopsies and cancer cells with a higher EMT status." (PMID 34936030, 2021). "IHC images revealed that CDKN2A, SELENOP, and TRPC1 were expressed at higher levels in endometrial carcinoma tissues compared to normal endometrial tissues, consistent with their mRNA upregulation in high-risk patients." (PMID 41244925, 2025). "Lastly, TRPC1 was upregulated in endometrial carcinoma, potentially enhancing tumor cell proliferation and invasive capabilities through its regulation of calcium signaling and crosstalk with hormone pathways." (PMID 41244925, 2025). "In endometrial cancer patients, the high expression of TRPC1 was correlated with low overall survival, even though the expression of TRPC1 was downregulated when comparing endometrial cancer with adjacent tissue samples." (PMID 35887266, 2022). "A total of 176 resectable endometrial carcinoma (EC) patients were recruited, then transient receptor potential channel 1 (TRPC1) protein and mRNA (of partial patients) in tumor tissues and normal endometria were determined." (PMID 35754147, 2022). "Overall, these results suggest that, like in tissue biopsies, the expression of TRPV2 and TRPC1 are associated with increased EMT status (or invasiveness), while TRPM4 expression is correlated with a low EMT status in endometrial cancer cells." (PMID 34936030, 2021). "Transient receptor potential channel 1 (TRPC1) promotes tumor growth and metastasis in endometrial carcinoma (EC) cell lines, whereas its clinical role in EC management remains unclear." (PMID 35754147, 2022). "The HPA database provided IHC images of endometrial cancer and normal endometrial tissues, allowing us to confirm the differential expression of CDKN2A, SELENOP, GSN, PGR, and TRPC1 at the protein level." (PMID 41244925, 2025).
neuroblastoma (7 papers, 2017 to 2025). Neuroblastoma (NB) is the most common solid, extracranial childhood tumor. "The activation of TRPC1 channels has been reported to induce neuroprotection against apoptosis in SH-SY5Y neuroblastoma cells, as well as to regulate SOCE channels and reduce DA neuronal cell death in the SN of TRPC1 KO mice." (PMID 33748103, 2021). "Most importantly, this study demonstrated that in SH-SY5Y neuroblastoma cells, MPP+ treatment decreased TRPC1 expression, TRPC1 interaction with the SOCE modulator stromal interaction molecule 1 (STIM1), and Ca2+ entry into the cells." (PMID 30082759, 2018). "Moreover, expression of mutant HTT in mouse neuroblastoma and MSNs showed enhanced SOCE activation, which was reversed by RNAi knockdown of Orai1, TRPC1, or STIM1." (PMID 40169779, 2025). "In the human SH-SY5Y neuroblastoma cell line, SOCE mainly depends on the activation of TRPC1." (PMID 33424550, 2020).
non-small cell lung carcinoma (7 papers, 2014 to 2022). A group of at least three distinct histological types of lung cancer, including non-small cell squamous cell carcinoma, adenocarcinoma, and large cell carcinoma. "Indeed, an upregulation of TRPC1 protein level in the G1 compared with G0 was observed in Ehrlich Lettré Ascites (ELA) cells while TRPC1silencing in non-small cell lung carcinoma cell lines decreased cyclin D1 and D3 expression levels, resulting in G0/G1 cell cycle arrest." (PMID 27183905, 2016). "In addition, TRPC1 was identified in human non-small cell lung carcinoma (NSCLC) cells as a major regulator for EGF signaling that affects cell proliferation." (PMID 36139480, 2022). "TRPC1 down-regulation along with SOC entry inhibition can result in reduced cyclin levels, G0/G1 cell cycle arrest and decreased cell growth in non-small cell lung carcinoma cell lines." (PMID 27443843, 2016). "For example, TRPC1 was confirmed to play different roles in tumorigenesis, inhibition of TRPC1 by siRNA or SOCE inhibitors could suppress the proliferation and invasion of cancer cells including nasopharyngeal carcinoma, malignant glioma and non-small-cell lung carcinoma." (PMID 34122115, 2021). "In non-small cell lung carcinoma (NSCLC) cells, we observed that TRPC1 was involved in SOCE and that TRPC1 depletion altered EGFR activation and induced a G0/G1 cell cycle arrest resulting in a dramatic decrease in cell growth." (PMID 29662626, 2018).
type 2 diabetes (7 papers, 2014 to 2025). "It was reported that TRPC1 genetic polymorphism was associated with type 2 diabetes in the Han Chinese population." (PMID 38885005, 2024). "Previous studies have reported that the TRPC1 gene polymorphisms are associated with type 2 diabetes and diabetic nephropathy in humans." (PMID 33450983, 2021). "Interestingly, single nucleotide polymorphism, rs7638459, in the TRPC1 gene was identified as a risk factor for developing type 2 diabetes in a Chinese population." (PMID 32872338, 2020). "TRPC1 was reported to reduce exercise-dependent protection against high-fat diet-induced obesity and type II diabetes." (PMID 32872338, 2020).
diabetic nephropathy (6 papers, 2021 to 2025). "An association among TRPC1 disfunction and diabetic nephropathy has also been proposed in animal models." (PMID 41009007, 2025). "In patients with diabetic nephropathy or Zucker diabetic rats compared with controls, decreased TRPC1 expression suggested that TRPC1 affected the development of diabetic nephropathy." (PMID 33754657, 2021). "Transient receptor potential canonical channel 1 (TRPC1), a target gene of HNF4α involved in mesangial cell contraction and glomerular function, is downregulated in patients with diabetic nephropathy, along with HNF4A expression, implicating this pathway in diabetic nephropathy pathogenesis." (PMID 41438090, 2025). "Reduced expression of TRPC1 has been reported in diabetic nephropathy." (PMID 38885005, 2024). "TRPC1 and the nuclear receptor, hepatic nuclear factor 4 alpha (HNF4 alpha), have been proposed as possibly involved in diabetic nephropathy, because TRPC1 expression was found to be reduced in this condition, in 12-week-old, and in 26-week-old diabetic db/db mice." (PMID 38885005, 2024). "TRPC1, which plays a role especially in diabetic nephropathy, is expressed almost everywhere, in renal mesangial cells, glomeruli, proximal tubule cells, and in the thin descending part of the Henle loop, but its exact function is still unknown." (PMID 33754657, 2021).
thyroid cancer (6 papers, 2020 to 2022). "Previously, we have reported that TRPC1 functions in thyroid cancer cells as a receptor-operated calcium channel and modulates thyroid cancer cell invasion." (PMID 34155535, 2021). "Indeed, TRPM2, TRPM7, TRPM8, TRPV2, and TRPC1 have shown to cause upregulation of MMP9 in a Ca2+-dependent manner in gastric, bladder, oral squamous, prostate and thyroid cancer cells respectively." (PMID 33132914, 2020). "We have recently shown that downregulation of calcium signals e.g., by knocking down the transient receptor potential canonical channel 1 (TRPC1), or the stromal interacting molecule 1 (STIM1), dramatically decreases invasion and proliferation of thyroid cancer cells." (PMID 36497320, 2022). "Additionally, TRPM2, TRPM7, and TRPC1 activity have been also correlated with MMP2 production in gastric, lung, pancreatic and thyroid cancer." (PMID 33132914, 2020).
diabetes (5 papers, 2017 to 2025). "For example, TRPC1 expression was found to be reduced in diabetes but any causal relationship was obscure, although TRPC1 was the first TRP channel cloned and identified in pancreatic beta cells." (PMID 38885005, 2024). "On the contrary, TRPC1 expression was found to be reduced in diabetes, but any causal relationship was unknown." (PMID 41009007, 2025). "Loss of TRPC1 may alter the regulation of cellular energy metabolism resulting in insulin resistance thereby leading to diabetes." (PMID 29074621, 2017). "In our model, we identified five differentially expressed diabetes-related genes, with GSN and PGR exhibiting heightened expression levels in the low-risk group, whereas CDKN2A, SELENOP, and TRPC1 demonstrated increased expression in the high-risk group." (PMID 41244925, 2025). "The same calcium-sensitive (calcineurin/NFAT), mitochondrial-regulating, transcriptional pathway (PGC-1α) that is activated by TRPC1 is downregulated in diabetes." (PMID 39120305, 2024). "To further validate the protein expression levels of the five key diabetes-related genes (CDKN2A, GSN, PGR, SELENOP, and TRPC1) identified in our prognostic model, we utilized IHC staining data from the HPA database." (PMID 41244925, 2025). "Accordingly, TRPC1/PGC-1 α-dependent oxidative muscle development is depressed in diabetes." (PMID 39120305, 2024). "Our analysis revealed a distinct stratification: while TRPC1, SELENOP, CDKN2A, GSN, and PGR all showed significant dysregulation in UCEC tissues compared to normal endometrium, only SELENOP, CDKN2A, and PGR exhibited diabetes-specific modifications in UCEC patients." (PMID 41244925, 2025). "In contrast, expression levels of TRPC1 and GSN remained comparable between diabetic and non-diabetic UCEC subgroups, indicating their involvement in general carcinogenesis rather than diabetes-specific pathways." (PMID 41244925, 2025).
epilepsy (5 papers, 2014 to 2025). A brain disorder characterized by episodes of abnormally increased neuronal discharge resulting in transient episodes of sensory or motor neurological dysfunction, or psychic dysfunction. "In some organs however, double deficient mice display significant phenotypes (e.g., TRPC1/4-/- mice in bladder innervation and epilepsy-induced neurodegeneration)." (PMID 25268281, 2014). "Furthermore, the hub genes of AD- and epilepsy-associated GCMs were captured by weighted key driver analysis (wKDA), including TRPC1, C2ORF40, NR3C1, KIAA0368, MMT00043109, STEAP1, MSX1, KL, and CLIC6." (PMID 34697589, 2021). "This may be the first report of a TRPC1 variant associated with epilepsy." (PMID 40944498, 2025). "Therefore, TRPC1 may be a shared genetic risk factor for AD and epilepsy." (PMID 34697589, 2021). "As first reported in 1995, TRPC1 protein can interact with TRPC4 and TRPC5 to form TRPC1/4/5 channels, which are significantly implicated in epilepsy." (PMID 34697589, 2021). "For example, the expression of TRPC1 is increased in cortical lesions of epilepsy patients and regulated by the mediation of astrocyte-induced epilepsy." (PMID 33748103, 2021). "TRPC1 mutations have not previously been reported in epilepsy, despite associations between TRPC channel function, epileptogenesis, and memory/learning." (PMID 40944498, 2025). "Furthermore, the hub genes of each AD- and epilepsy-associated GCM were captured, including TRPC1, C2ORF40, NR3C1, KIAA0368, MMT00043109, STEAP1, MSX1, KL, and CLIC6." (PMID 34697589, 2021). "Consequently, TRPC1 is the potential target for the treatment of epilepsy." (PMID 34697589, 2021). "It is generally known that TRPC1/4 channels can lead to the excitotoxicity and epileptiform burst firing in the CA1 and the lateral septum, which are pathophysiological elements of epilepsy." (PMID 34697589, 2021). "TRPC1, TRPC3-7, TRPM2, TRPM7, TRPV1, TRPV4, and TRPA1 have been shown to be involved in epilepsy." (PMID 33748103, 2021). "Notably, TRPC1 also showed colocalization with GFAP in reactive astrocytes, indicating that the channel may aid in astrocyte modulation of epilepsy." (PMID 36902145, 2023).
heart failure (5 papers, 2018 to 2024). Inability of the heart to pump blood at an adequate rate to meet tissue metabolic requirements. "The TRPC family of proteins (TRPC1-7) function as both homo- and hetero-tetramers, and both Trpc1 and Trpc3 as well as Trpc6 have been implicated in heart failure induced by pressure overload." (PMID 35096991, 2021). "In humans, studies have shown increased TRPC1 expression in response to heart failure and hypertrophic cardiomyopathy." (PMID 39682767, 2024). "Expression of TRPC1 was elevated in patients with hypertrophic cardiomyopathy and heart failure compared to healthy donor hearts." (PMID 36620209, 2022). "A number of studies have demonstrated the potential of TRPC1, 3 and/or 6 channels as therapeutic targets for heart failure, predominantly using in vivo models of pressure overload in male mice." (PMID 35096991, 2021). "Here we show that the knockout of transient receptor potential canonical (TRPC) channel isoforms TRPC1 and TRPC6 can ameliorate LPS-challenged heart failure and prolong survival in mice." (PMID 36460692, 2022).